FCRL5 (Fc receptor like 5)
Diseases named in the same sentence as FCRL5 in open-access papers (continued):
Sharing a sentence is not in itself a finding about the gene and the disease.
infection (18 papers, 2016 to 2025). The state of being infected such as from the introduction of a foreign agent such as serum, vaccine, antigenic substance or organism. "CCR6+ cells associated with poor infection outcomes also expressed high levels of the Fc-like inhibitory receptor FcRL5, which has been found to be upregulated among MBCs with reduced capacity to differentiate into antibody-secreting cells." (PMID 34128836, 2021). "Interestingly, FCRL5, which is associated with the function of B memory cells, was highly upregulated at 1 day post‐Alpha or ‐Delta infection in PBMCs compared with those in PBMCs post‐Proto or ‐Beta infection." (PMID 38020713, 2023). "Between month 6 and month 12 post-infection, persistent Bm cell clones upregulated genes associated with CD21–CD27–FcRL5+ Bm cells, including TBX21, ITGAX and FCRL5." (PMID 37106039, 2023). "GC-derived FCRL5+ MemBs share transcriptomic and repertoire properties with atypical B cells found in aging and infection and localize to the marginal zone, suggesting a similar contribution to recall responses." (PMID 37341394, 2023). "MSP121-specific AMB sorted during chronic P. chabaudi infection, and MSP121-specific Bmem sorted after resolution of the infection shared the expression of a series of mouse memory markers, including Cd80, Fcrl5, Nt5e (CD73), and Cd86." (PMID 30387712, 2018). "Activation of parasite-specific IgM+ classical MBCs during infection might result in expansion of FcRL5+ IgM+ MBC subsets, in particular activated MBCs." (PMID 34758841, 2021). "However, the level of FCRL5 expression on P. chabaudi-specific Bmem detected after resolution of the infection was noticeably higher than that of naïve B cells both at the protein and mRNA levels." (PMID 30387712, 2018). "Thus, after resolution of the infection, high expression of FCRL5 identifies P. chabaudi-specific Bmem." (PMID 30387712, 2018). "However, it is tempting to speculate that long-lived FcRL5+ classical MBCs undergo high rates of recall in response to frequent recurrent infections and are thus rapidly removed from the memory pool." (PMID 34758841, 2021). "Thus, after resolution of the infection, high expression of FCRL5 acted as a universal Bmem marker." (PMID 30387712, 2018). "Expression of Blimp-1, T-bet, FcRL5 and CD71 were increased on S+ Bm cells during acute infection compared with months 6 and 12 post-infection, and S+ Bm cells underwent strong proliferation during the acute phase." (PMID 37106039, 2023). "(E) Heat map showing expression levels of different genes on splenic FCRL5— and FCRL5hi MSP121-specific B cells sorted at 155dpi, and MSP121-specific B cells sorted before infection (naïve), determined by RNAseq analysis." (PMID 30387712, 2018). "Analysis of FcRL5 expression on DN3 cells reveals that this population appears to normally express low levels of FcRL5 and expression is variably increased on DN3 cells with severe SARS-CoV-2 infection and when compared to immunized individuals or those with mild infection." (PMID 36131937, 2022). "We saw no increase in FCRL5+ B cells in the blood of aged naive mice, indicating that expansion of this population is due to infection rather than age." (PMID 27583554, 2016). "The lack of FcRL5 and T-bet expression in CD11c+ memory B cells observed here may point to differences in the immune response to vaccination and infection." (PMID 39466842, 2024). "The expression of T-bet, in parallel with a surface marker profile that includes the presence of FcRL5 and CD11c and the absence of CD21, has previously been reported on activated B cells shortly after vaccination and infection, and is associated with long-lived humoral immunity." (PMID 34936684, 2021).
cancer (3 papers, 2015 to 2025). A tumor composed of atypical neoplastic, often pleomorphic cells that invade other tissues. "CD307c (Fc receptor-like 5) is differentially expressed in cancer cells." (PMID 27655682, 2016).
blood cancers (1 paper, 2024). "Among the proteins associated with risk of haematological cancers, we identified associations with risk of multiple blood cancers for members of the FC-receptor protein [FCRL1, FCRL2, FCRL3, FCRL5, FCRLB] and TNF receptor families [TNFRSF4, TNFRSF9, TNFRSF13B, TNFRSF13C, TNFSF13B, TNFSF13]." (PMID 38750076, 2024).
infectious disease (1 paper, 2025). A disorder directly resulting from the presence and activity of a microbial, viral, or parasitic agent in humans. "Although present in healthy individuals and capable of mediating protective immune responses, T-bet+ B cells coexpressing combinations of other markers (e.g., Fc receptor like 5 [FCRL5]/CXCR3) are commonly pathogenic activated effectors in autoimmune and infectious diseases with female bias." (PMID 40359016, 2025).
FCRL5 also shares sentences with these, for which no sentence is quoted: multiple myeloma (14 papers); hematologic malignancies (3); chronic lymphocytic leukemia (2); diffuse large B-cell lymphoma (2); granulomatosis with polyangiitis (2); mantle cell lymphoma (2); acute myeloid leukemia (1); AIDS (1); allergic reactions (1); ankylosing spondylitis (1); B cell lymphomas (1); chronic hepatitis B (1); diabetes (1); emphysema (1); follicular lymphoma (1); Immunodeficiency (1); inflammatory bowel disease (1); leukemia (1); lymphoma (1); mastitis (1); metastatic tumors (1); neutropenia (1); peripheral neuropathy (1); tetanus (1).